TLR4 (toll like receptor 4)
Diseases named in the same sentence as TLR4 in open-access papers (continued):
Sharing a sentence is not in itself a finding about the gene and the disease.
lung cancer (continued). "Toll-like receptor 4 (TLR4), an membrane-bound receptor, may serve as a binding site and signaling transducer of LMF which rapidly induces ROS-mediated endoplasmic reticulum (ER) stress and then activates the PERK-ATF4-CHOP pathway to trigger lung cancer cell death and suppress tumor progression." (PMID 28928376, 2017). "Additional regulators of the TLR-4 smoke signaling pathway may unveil new therapeutic targets that can be inhibited to down regulate the expression of MMPs in the presence of cigarette smoke, which would likely be beneficial in the treatment of both COPD and lung cancer." (PMID 25664615, 2015). "In parallel, TLR4 and CD68 were abundantly expressed and co-localized in cancerous areas but not adjacent tissues in samples from lung cancer patients." (PMID 36542153, 2022).
hepatocellular carcinoma (130 papers, 2009 to 2026). A malignant tumor that arises from hepatocytes. "They conducted a case–control study at a single center, genotyping TLR4 sequence variants using the polymerase chain reaction (PCR) and direct sequencing in 426 hepatocellular carcinoma cases and 438 controls." (PMID 37896221, 2023). "Taken together, the present results strongly indicate that GGA causes pyroptotic cell death in human hepatoma-derived HuH-7 via TLR4 signalling." (PMID 32270855, 2020). "In the present work, we examined the role of NADPH oxidase 4 (Nox4) in LPS-induced TLR4 responses in human hepatoma cells and wildtype and Nox4-deficient mice." (PMID 29085012, 2017). "Polymorphisms of the TLR4 gene are associated with delayed progression of liver fibrosis and reduced risk of development of hepatocellular carcinoma." (PMID 26347404, 2015). "TLR4 shows pro-tumorogenic effects, with mice deficient in TLR4 at reduced risk of developing gastrointestinal and hepatocellular cancer." (PMID 25309546, 2014). "Specifically, we firstly described the positive association between four 5′-UTR polymorphism (rs10759930, rs2737190, rs10116253 and rs1927914) and one intron polymorphism (rs1927911) of TLR4 gene and the risk of hepatocellular carcinoma." (PMID 21559380, 2011). "Collectively, these results suggested that the risk of hepatocellular carcinoma was associated with TLR4 sequence variation." (PMID 21559380, 2011). "In haplotype analysis, one haplotype (GCCCTTAG) of TLR4 was associated significantly with decrease of the occurrence of hepatocellular carcinoma (OR, 0.556, 95% confidence interval [CI], 0.407–0.758, P = 0.000)." (PMID 21559380, 2011). "This study aimed to investigate the temporal relationship of single nucleotide polymorphisms of TLR4 and the risk of hepatocellular carcinoma, a single center-based case-control study was conducted." (PMID 21559380, 2011). "Our results in this study suggested that inherited variation in TLR4 influences the risk of hepatocellular carcinoma." (PMID 21559380, 2011). "A systematic genetic analysis of sequence variants of TLR4 by evaluating ten single-nucleotide polymorphisms was performed from 216 hepatocellular carcinoma cases and 228 controls." (PMID 21559380, 2011). "Six single nucleotide polymorphisms of the TLR4 in the 5′-untranslated region and intron were associated with risk of hepatocellular carcinoma." (PMID 21559380, 2011). "In the present study, three SNPs (rs1927911), which located in the region of intron of TLR4, appeared to decrease risk of hepatocellular carcinoma (OR, from 0.572 to 0.607, P<0.01) significantly also." (PMID 21559380, 2011). "In conclusion, our study provided evidence of a close association between TLR4 sequence variants and hepatocellular carcinoma." (PMID 21559380, 2011). "The 5′-UTRs polymorphisms of TLR4 presumably affect transcription and/or translation among individuals with hepatocellular carcinoma." (PMID 21559380, 2011). "NE can enter tumor cells and degrade tumor suppressors or remodel the extracellular matrix, while HMGB1 (a damage-associated molecular pattern) engages receptors like RAGE/TLR4 on hepatoma cells to activate NF-κB signaling, activating a pro-survival, pro-proliferation program." (PMID 41516032, 2025). "In human hepatocellular carcinoma, it reported that the expression of TLR4 was associated with stemness of CSCs and TLR4 promoted tumor invasion, metastases, and might serve as a surface marker for CSCs." (PMID 33588867, 2021). "We found that GGA causes UPR via TLR4 signalling, which may be linked to cell death in hepatoma cells." (PMID 32270855, 2020). "We hypothesized that single-nucleotide polymorphisms of TLR4 are related to the occurrence of hepatocellular carcinoma." (PMID 21559380, 2011). "Alteration in TLR4 activity influences innate immunity and inflammation, which in turn may affect hepatocellular carcinoma susceptibility." (PMID 21559380, 2011).
hepatocellular carcinoma (continued). "Our results suggested that mutation of TLR4 gene in 5′-UTR might reduce the occurrence of hepatocellular carcinoma." (PMID 21559380, 2011). "Association between hepatocellular carcinoma and TLR4 single nucleotide polymorphisms." (PMID 21559380, 2011). "In our study, the TLR4 SNPs may potentially exert regulator effects and therefore might decrease the risk for hepatocellular carcinoma." (PMID 21559380, 2011). "TLR4 single nucleotide polymorphisms may play an important protective role in the development of hepatocellular carcinoma." (PMID 21559380, 2011). "In this study, the genetic diversity in TLR4 was examined comprehensively to validate our hypothesis that inherited differences in TLR4 were associated with hepatocellular carcinoma." (PMID 21559380, 2011). "Association of haplotypes in TLR4 with hepatocellular carcinoma." (PMID 21559380, 2011). "In human hepatocellular carcinoma (HCC), increased stem-like traits are associated with TLR4 expression, and the expression of TLR4 in HCC cells closely correlates with their invasive and migratory abilities." (PMID 41488647, 2025). "Increased stem-like properties were also associated with high TLR4 expression in mice models of hepatocellular carcinoma (HCC)." (PMID 37368660, 2023). "First, LPS binding to TLR4 on the surface of HSCs promotes the secretion of proliferative factors, inhibits apoptosis of hepatoma cells, and enhances their survival ability." (PMID 40990659, 2026). "Immunoprecipitation studies in hepatocellular carcinoma cells have demonstrated that TREM1 forms a complex with TLR4 to activate downstream signaling." (PMID 41394801, 2025). "Through the study of hepatocellular carcinoma (HCC) patients caused by hepatitis B virus (HBV), TLR3 and TLR4 polymorphisms served as biomarkers of virus‐related tumors." (PMID 40727252, 2025). "NETs can modulate the expression of genes linked to oxidative phosphorylation in naïve CD4+ T cells via TLR4 signaling, inducing their differentiation into Tregs and facilitating the progression from nonalcoholic steatohepatitis to hepatocellular carcinoma." (PMID 40365275, 2025). "HAND2-AS1 reverses lenvatinib resistance in hepatocellular carcinoma by promoting ferroptosis through the TLR4/NOX2/DUOX2 pathway via miR-219a-1-3p, with low HAND2-AS1 levels linked to early recurrence." (PMID 39315094, 2024). "In hepatocellular carcinoma, TLR4 induces human hepatocellular carcinoma through a variety of mechanisms, including increased production of pro-inflammatory and malignant-related molecules." (PMID 38463226, 2024). "TLR4’s higher expression in relapsing hepatocellular carcinoma patients has recently been linked to its newly discovered regulatory role in the enhancement of stem properties in HCC cells via the TLR4–AKT–SOX2 pathway." (PMID 38473265, 2024). "Overexpression of TLR4 in hepatocellular carcinoma contributes to the formation of immunosuppressive microenvironment." (PMID 39034996, 2024). "Another example is in hepatocellular carcinoma, where the activation of TLR4 and TLR9 by NETs led to upregulation of COX2, a potent inflammatory mediator, which enhanced the invasiveness of HCC cells." (PMID 36050539, 2023). "In this study, we investigated the potential of TLR4 to improve the treatment of hepatocellular carcinoma (HCC)." (PMID 37345131, 2023). "Recently, it was reported that CXCL10 contributes to hepatocellular apoptosis through TLR4 on MDSCs instead of its common receptor—CXC motif receptor 3—in patients with hepatocellular carcinoma (HCC), thus leading to cancer recurrence." (PMID 36911674, 2023). "In summary, it was shown that the administration of exogenous GGA [XI] to hepatoma cells acts in an inhibitory manner against hepatocarcinogenesis by inducing pyroptosis, a form of inflammatory cell death, via TLR4, which is upregulated in hepatoma cells." (PMID 37247782, 2023).
hepatocellular carcinoma (continued). "In conclusion, the TLR4 signaling pathway plays a critical role in liver physiology and pathology, including the development and progression of hepatocellular carcinoma." (PMID 37896221, 2023). "TLR4 is upregulated in HBV-related hepatoma cells, and promotes their growth, while inhibiting the apoptosis of these cells, by activating the extracellular signal-regulated kinase (ERK)-1/2 signaling pathway." (PMID 35251017, 2022). "In animal models of hepatocellular carcinoma as well as in pancreatic cancer, LPS released from GM is able to activate Toll-like receptor 4 (TLR4) and negatively modulate immune responses." (PMID 35370685, 2022). "Most recently, we reported that GGA induces Toll-like receptor 4 (TLR4)-mediated pyroptosis in human hepatoma-derived cells." (PMID 34564450, 2021). "Most recently, we concluded that GGA induces Toll-like receptor 4 (TLR4)-signaled pyroptosis in human hepatoma cells." (PMID 34869922, 2021). "Here, we focused on miR-877 because of its association with processes relevant to SCCC, such as p16 activation, restoration of paclitaxel sensitivity, and TLR4 inhibition, in bladder cancer, hepatocellular carcinoma, and glioma, respectively." (PMID 33917510, 2021). "There is growing experimental evidence that saturated as well as unsaturated FAs are able to affect the activity of membrane proteins, e.g., PA activates TLR4 (Toll-like receptor 4) in hepatocellular carcinoma cells and epithelial rat kidney-derived cells." (PMID 33924206, 2021). "Geranylgeranoic acid (GGA) was developed as a preventative agent against second primary hepatoma, and was reported to induce cell death in human hepatoma cells via Toll-like receptor 4 (TLR4)-mediated pyroptosis." (PMID 34869922, 2021). "Recently, GGA was reported to induce cell death in human hepatoma cells via TLR4-mediated pyroptosis." (PMID 34564450, 2021). "The response to lenvatinib revealed two genes unique to Huh7 cells, 14 unique to HepG2 cells, and two genes (IL1A and TLR4) upregulated in both human hepatoma cell lines." (PMID 32397371, 2020). "Genetic TLR4 inactivation, gut microbial deprivation or germ-free status decrease the development of hepatocellular carcinoma hepatocellular carcinoma in almost 80% of cases." (PMID 32756323, 2020). "In hepatocellular carcinoma TLR4 expression was classified as a possible carcinogenic agent, due to its ability to increase quantity of several pro-inflammatory and malignancy-related molecules such as NANOG, Caspase-1 and others." (PMID 30976817, 2019). "Upregulation of miR-122 significantly inhibited TLR4 expression in hepatoma cells, including in hepatoma cells with the induction of LPS, while knocking down miR-122 increased TLR4 expression." (PMID 31340754, 2019). "We present evidence that Nox4 mediates LPS-induced TLR4 signaling in human hepatoma cells and murine hepatocytes as well as liver and plasma in whole mice in vivo." (PMID 29085012, 2017). "Tlr4 is the receptor for endotoxin, which is an important mediator of liver inflammation associated with NAFLD and hepatocellular carcinoma." (PMID 29113135, 2017). "In summary, the present study provides evidence that Nox4 mediates LPS-TLR4 signaling in human hepatoma cells and murine hepatocytes in vitro through the TLR4-Nox4-NF-κB and TLR4-Nox4-AP-1 signaling pathways." (PMID 29085012, 2017). "Stimulation of Toll-like receptor 4 (TLR4) by bacterial lipopolysaccharide (LPS) initiates inflammation and promotes development of hepatocellular carcinoma and other liver diseases." (PMID 29085012, 2017). "Environmental hyaluronan fragments from hepatoma cells produced PD-1high regulatory B cells via TLR4 activation, during which TLR4-mediated Bcl-6 upregulation was critical." (PMID 29299180, 2017). "Furthermore, high expression of TLR4 in human hepatocellular carcinoma (HCC) tissues has also been found associated with poor survivals in patients." (PMID 29029545, 2017).
hepatocellular carcinoma (continued). "Recently, some studies showed that the PRDX1 was overexpressed in various human tumors such as breast, lung, urinary, and hepatocellular carcinoma, and its interaction with toll-like receptor 4 (TLR4) stimulates tumor angiogenesis in prostatic carcinoma." (PMID 27362486, 2016). "This was impaired by TLR4 inhibition in about 40%, which leads to the development of hepatocellular carcinoma." (PMID 26347404, 2015). "The liver is constantly exposed to gut microbiota-derived products that activate hepatic toll-like receptor 4 (TLR4), which has been implicated in the development of liver inflammation and fibrosis, and even hepatocellular carcinoma." (PMID 25479248, 2014). "Gut microbiota-derived products activate hepatic TLR4, which has been implicated in the development of alcoholic steatohepatitis, NASH, liver fibrosis and hepatocellular carcinoma." (PMID 25479248, 2014). "In hepatocellular carcinoma, neutrophils were activated by tumor-derived hyaluronan binding to TLR4 on their surface and promoted tumor cell motility." (PMID 23423155, 2013). "Chi Square analysis of the genotypes revealed significantly different distributions in six TLR4 SNPs (rs10759930, rs2737190, rs10116253, rs1927914, rs10759932 and rs1927911) between the group with hepatocellular carcinoma and the control group (P<0.05)." (PMID 21559380, 2011). "Lipopolysaccharide (LPS) derived from GM could induce hepatocellular carcinoma by activating TLR4 in immune cells." (PMID 38419642, 2024). "SCFAs have been reported to delay hepatocellular carcinoma development in HBx transgenic mice, while Enterococcus faecalis, through its expression of gelE, enhances IB permeability and promotes tumor formation in a TLR4-Myd88 dependent manner." (PMID 38474727, 2024). "Toll-like receptor 4 in cancer cells increases both cell survival and proliferation in hepatocellular carcinoma (Lipopolysaccharide-induced toll-like receptor 4 signaling in cancer cells promotes cell survival and proliferation in hepatocellular carcinoma - PubMed [WWW Document], 2013)." (PMID 37608943, 2023). "However, even if such an assumption can be made, in experiments with specific inhibitors of TLR4 or gene knockdown, the most upstream signal for GGA-induced cell death in hepatoma is TLR4 activation." (PMID 37247782, 2023). "In accordance with our results, recent evidences have shown that HIF-1α could mediate the expression of TLR4 in pancreatic cancer, oral squamous cell carcinoma, and hepatocellular carcinoma under hypoxia." (PMID 35464826, 2022). "Specifically, the overexpression of HBx in hepatic and hepatoma cell lines activates TLR4 downstream signaling components such as myeloid differentiation primary response 88 (MyD88), IRAK1, and nuclear factor-kappaB (NF-κB), contributing to the secretion of IL-6, a major pro-inflammatory cytokine." (PMID 36298831, 2022). "It was reported that its receptor (TLR4) could mediate pyroptosis in human hepatoma-derived HuH-7 cells." (PMID 35308143, 2022). "The clustering of regulatory T (Treg) cells in hepatoma cell lines could be indirectly promoted by the interaction of TLR4 with macrophages, accompanied by the upregulation of IL-10 and C-C class chemokine 22 (CCL22) expression." (PMID 35572649, 2022). "Although the present findings are limited to a single cell line of human hepatoma-derived HuH-7, TLR4 was reported to have a pathological role during chronic hepatic inflammation and may be a cause of human hepatoma." (PMID 32270855, 2020). "Moreover, gut microbiota and TLR4 appear to be required for the promotion of hepatocellular carcinoma (HCC), whose pathogenesis is enhanced by chronic liver inflammation and fibrosis." (PMID 32850884, 2020). "MiR-122 might target TLR4 and regulate host innate immunity in hepatoma cells, which revealed a new molecular mechanism of miR-122 on the regulation of innate immunity." (PMID 31340754, 2019).